CDKN1A (cyclin dependent kinase inhibitor 1A)
Diseases named in the same sentence as CDKN1A in open-access papers (continued):
Sharing a sentence is not in itself a finding about the gene and the disease.
infection (37 papers, 2010 to 2025). The state of being infected such as from the introduction of a foreign agent such as serum, vaccine, antigenic substance or organism. "Among these, p15 (CDKN2B) and p21 (CDKN1A), which are cyclin-dependent kinase inhibitors implicated in the suppression of cell proliferation under several stresses, were upregulated upon infection." (PMID 24812617, 2014). "Coinciding with peak viral load, the expression of Slfn1 and Cdkn1a peaked by 2 dpi but remained elevated throughout infection (Stress Response panel)." (PMID 38107402, 2023). "This relationship is however confounded during infection, by equally strong correlations between fetal viral load and both CDKN1A expression and thyroid hormone abundance." (PMID 35189966, 2022). "Prior to the infection experiments, senescence in HeLa and HepG2 cells after BrdU treatment was confirmed by determining the expression of CDKN1a which is a marker of proliferation arrest in senescent cells." (PMID 34746026, 2021). "To further characterize the senescence phenotype, we performed staining for the senescence marker P21 (CDKN1A) in the cultures 96 h post-infection." (PMID 34452468, 2021). "There was little difference in CDKN1A expression after Ad-null and Ad-shSOX2 infection in TE1 cells and TE4 cells." (PMID 29262545, 2017). "After retesting shRNAs targeting the top screen candidates, we found that infection with shRNAs targeting four of these genes (CDKN1A, MTOR, MYOT, and UBE2E1) resulted in a consistent bypass of OSKM-induced senescence." (PMID 29138277, 2017). "On the other hand, CDKN1A expression was clearly different after Ad-null and Ad-shSOX2 infection in EBC2 cells." (PMID 29262545, 2017). "Indeed, infection increased expression of Cdkn1a in the mPFC, cerebellum and hippocampus, and of Tnf in the mPFC and hippocampus." (PMID 37596606, 2023). "Notably, these complexes included Cdkn1a and Ccnda, which highlights a possible G1 cell cycle arrest early in infection." (PMID 38107402, 2023). "Knocking down CDKN1A increased both the M1 infection and viral titer in these cell lines." (PMID 33037696, 2020). "It is remarkable that p21 (CDKN1A) is upregulated in the early infection, suggesting that T. cruzi infection triggers a transient cell cycle arrest which may allow the cell to repair the damage." (PMID 24812617, 2014). "The upregulation of the genes expressing the cell survival factor osteopontin (Spp1) and the Cyclin-dependent kinase inhibitor P21 (Cdkn1a), which is upregulated in response to tissue injury, is evidence of the host's attempt to counteract the damaging effects of the infection." (PMID 21949840, 2011). "To determine the expression of cellular senescence-related mRNA, we analyzed CDKN2A, CDKN1A, MMP3, and Lamin B1 in the slices 8 d post infection." (PMID 37163429, 2023). "Further knockout of CDKN1A in HCT‐15 and PANC‐1 cell lines by shRNA also increased the infection and titer of M1 virus." (PMID 33037696, 2020). "Following infection, let-7c, miR-34a or miR-124a were upregulated, and they targeted and downregulated p21 and TASK1 (also known as CDKN1A and KCNK3, respectively) cellular proteins." (PMID 25717002, 2015).
infection (continued). "Of the tissues evaluated in the present study, gene expression in the HRT was the most severely impacted by infection, with significant decreases in all three cell cycle promoters (CDK1, CDK2 and CDK4) and the largest increase in expression of their inhibitor CDKN1A." (PMID 35189966, 2022). "However, in response to infection, male mice exhibited higher expression levels of CDKN1B, and CTNNB1 (KO, 1A3), TCF4 (1A0, 6A2), TAP1, and TAP2, (1A0), CDKN1A, (1A3, 6A2), MARCO, and MMP12 (1A3), CCND1, CDK2, IRF and MYC (6A2) compared to females." (PMID 32670284, 2020). "Exogenous hsa_circ_0000280 did not alter CDKN1A expression after si-ELAVL1 infection." (PMID 36477660, 2022). "In addition, RBM38 may regulate LTNPs through the stability of CDKN1A and the down-regulation of MS4A6A may modify infection of HIV-1 in LTNPs." (PMID 30626383, 2019). "Hepatic tissue showed a significant increase in CDKN1A in highly infected fetuses, but all three CDK genes were found to be stable regardless of fetal infection status." (PMID 35189966, 2022).
adenocarcinoma (10 papers, 2016 to 2025). A common cancer characterized by the presence of malignant glandular cells. "Likewise, patients with adenocarcinoma with high CDKN1A expression showed significantly poorer progression‐free survival compared to those with low CDKN1A expression." (PMID 36054146, 2022). "It should be noted that CDKN1A was the target gene with the highest number of significant negative correlations (p < 0.05) in both adenocarcinoma (miRNA-512-5p, miRNA-512-3p, miRNA-520a-3p and miRNA-520h) and SCC (miRNA-515-3p, miRNA-519b-3p, miRNA-520a-3p and mir-372-3p)." (PMID 36900258, 2023).
renal diseases (5 papers, 2013 to 2025). "Knockout studies suggest a protective role for Cdkn1a in kidney disease and Btg2 expression was also shown to be increased in the ischemic, but not contralateral control, kidney." (PMID 33946347, 2021). "At the early time point (24 h), CDKN1A (p21CIP1) a gene known to stop cell-cycle progression was the most strongly up-regulated gene, followed by GDF15, a member of the TGF beta superfamily reported to be elevated in patients with renal diseases." (PMID 23457584, 2013).
hematologic disease (3 papers, 2015 to 2024).
kidney (3 papers, 2021 to 2023). "Cdkn1a encodes P21 and is increased during chronic alcohol feeding and contributes to modulate alcoholic fatty liver in mice via the ROS-HNE-P21 pathway." (PMID 35565941, 2022). "The upregulated genes included known acute kidney injury markers such as Havcr1 (Kim1), S100a6, Clusterin, Cdkn1a, and Spp127–29." (PMID 37898693, 2023).
metabolic disorders (3 papers, 2025). "CDKN1A plays a significant role in tumorigenesis, aging, and metabolic diseases, and is thus considered a potential target for therapy and a prognostic marker." (PMID 40515824, 2025). "First, what is the relationship among CDKN1A, FOS, ITGB4, and MAP2K1 in metabolic disorders after MI." (PMID 39069811, 2025).
neurodegenerative disease (3 papers, 2020 to 2022). A disorder of the central nervous system characterized by gradual and progressive loss of neural tissue and neurologic function. "These include Spon2, Adam19, Arntl, Cdkn1a, Cry2, Per2, Per3, Wee1, Rcan1, Slc41a3, Errfi1, and Bhlhe41, which are related to numerous cardiovascular and degenerative diseases of other organs as well as varying aging processes." (PMID 33668521, 2021). "In particular, CDKN1A, which together with interacting zinc finger protein 1 (CIZ1) plays a key role in DNA replication and cell cycle progression through the G1/S checkpoint, may contribute to neurodegenerative diseases." (PMID 35592696, 2022).
CNS tumor (2 papers, 2009 to 2019). "Among CNS tumors, gains and losses were distributed throughout the genome with some chromosome arms having a higher rate of either gain (7q, 8q, 12q) or loss (9p, specifically CDKN1A and CDKN2B)." (PMID 31133068, 2019). "To determine the clinical relevance of the polymorphisms in codon 31 and at the 3’UTR site, we determined their correlation with CDKN1A protein expression in the CNS tumor samples." (PMID 20169278, 2009). "One of the purposes of the present study was to evaluate CDKN1A protein expression in CNS tumors, in order to correlate the expression levels with the development and degree of malignancy of these tumors." (PMID 20169278, 2009). "The aim of our study was to determine the prevalence of genetic polymorphisms (codon 31 and 3’ untranslated region, 3’UTR) and protein expression of the cyclin-dependent kinase inhibitor 1A (CDKN1A) gene in patients with and without CNS tumors." (PMID 20169278, 2009).
genetic diseases (2 papers, 2014 to 2022).
Neurological Disease (2 papers, 2015 to 2019). "Among these genes, Ch25h, Trpa1, Cdkn1a, Ly6g6e, Six3, and Opalin are potentially associated with neurological diseases; Lcn2, Serpina3f, Lao1, Trim29, bcl3, and Gkn3 are associated with inflammatory response." (PMID 30804943, 2019). "The most prominent pathway identified by IPA analysis indicated that this cluster was enriched in "Neurological Disease"-related genes (Adcyap1, Bdnf, CA12, Cdkn1a, Vgf)." (PMID 25803291, 2015).
bacterial infection (1 paper, 2024).
vasculopathy (1 paper, 2020). "For example, we identified a subnetwork involving endothelial IL33 ↔ macrophage CXCL13 ↔ fibroblast CDKN1A; each component within this subnetwork is associated with vasculopathy, and here we suggest that they interact during metabolic pathology in the aorta." (PMID 34692110, 2020).
CDKN1A also shares sentences with these, for which no sentence is quoted: nasopharyngeal carcinoma (5 papers); Cirrhosis (4); pancreatic ductal adenocarcinoma (4); type 2 diabetes (4); Anxiety (3); ataxia telangiectasia (3); B cell lymphomas (3); cardiomyopathy (3); cardiovascular disease (3); Cdt (3); depression (3); Hypertension (3); progeria (3); acute promyelocytic leukemia (2); Arrhythmia (2); asthma (2); autism (2); bladder urothelial carcinoma (2); breast invasive carcinoma (2); Fanconi anemia (2); Fulminant hepatitis (2); Hodgkins lymphoma (2); hyperparathyroidism (2); inflammation (2); laryngeal squamous cell carcinoma (2); laryngeal tumors (2); lung squamous cell carcinoma (2); memory impairment (2); mesothelioma (2); myelodysplastic syndrome (2).
A further 130 diseases each share a sentence with CDKN1A in 2 papers or fewer.